LINC00996 (long independently transcribed non-coding RNA 996)
Gene: Long non-coding RNA gene on chromosome 7 (150,433,277 to 150,448,141, forward strand). Ensembl gene ENSG00000242258.
Diseases named in the same sentence as LINC00996 in open-access papers:
LINC00996 is named in the same sentence as 12 diseases in open-access papers, as found by Europe PMC text mining. Sharing a sentence is not in itself a finding about the gene and the disease. The quoted sentences say what the papers report.
colorectal cancer (5 papers, 2021 to 2024). A primary or metastatic malignant neoplasm that affects the colon or rectum. "The prognostic function of LINC00996 is also implicated in colorectal cancer, head and neck cancer, and multiple myeloma." (PMID 36105077, 2022). "LINC00996 has been identified as a potential lncRNA biomarker for early diagnosis across various cancer types, including colorectal cancer, bladder cancer, pulmonary adenocarcinoma and squamous cell carcinoma, ovarian cancer, and so on." (PMID 39220187, 2024).
lung adenocarcinoma (2 papers, 2022 to 2025). A carcinoma that arises from the lung and is characterized by the presence of malignant glandular epithelial cells. "Among the nine MRLs identified, LINC00996 is a novel tumor suppressor that reduces tumorigenesis and metastasis of lung adenocarcinoma via signaling pathways, such as JAK-STAT3 and cell adhesion molecules, similar to antigen processing and presentation." (PMID 39352634, 2025).
lung carcinoma (2 papers, 2021 to 2022). "It is still indispensable to further discuss whether Linc00996 plays a key role in other pathological subtypes of lung cancer." (PMID 36118847, 2022). "Furthermore, function enrichment result of Disease Ontology, Gene Ontology and Kyoto Encyclopedia of Genes and Genomes analyses indicated that the potential value of LINC00996 goes beyond lung cancer and immunology." (PMID 34394068, 2021). "However, Linc00996 is rarely reported in lung cancer, and the molecular mechanism remains elusive." (PMID 36118847, 2022).
squamous cell carcinoma (2 papers, 2022 to 2024). A carcinoma arising from squamous epithelial cells. "LINC00996 is a potential therapeutic target in pulmonary adenocarcinoma and squamous cell carcinoma." (PMID 36051690, 2022).
head and neck squamous cell carcinoma (1 paper, 2022). A squamous cell carcinoma that arises from any of the following anatomic sites: lip and oral cavity, nasal cavity, paranasal sinuses, pharynx, larynx, and salivary glands. "LINC00996 was associated with immune cell infiltration status and immunotherapy responses in head and neck squamous cell carcinoma." (PMID 36266640, 2022).
tumor (8 papers, 2021 to 2025). "FENDRR, EP300-AS1, SYNPR-AS1, LINC00996, and ATP13A4-AS1 are tumor suppressor genes whose overexpression is associated with favorable outcome, whereas the other genes in the model are oncogenes." (PMID 36060239, 2022). "The role of LINC00996 in CRC has been systematically explored in a study, indicating that LINC00996 is downregulated in CRC and its downregulation is associated with unsatisfactory prognosis and tumor progression." (PMID 35616307, 2023). "Linc00996 could affect the level of immune infiltration by mediating gene expression levels in these tumor-infiltrating immune cells and participating in immune-related signaling pathways." (PMID 36118847, 2022). "The two experiments powerfully demonstrated that Linc00996 serves as a tumor silencer in LUAD." (PMID 36118847, 2022). "Thus, the genomic and proteomic analyses strongly suggest that LINC00996 is a potential target of tumor immunology." (PMID 34394068, 2021). "LINC00996, RPARP‐AS1, SND1‐IT1, and TMPO‐AS1 have emerged as key molecules in the intricate network of tumour pathophysiology, potentially influencing NSCLC progression and patient outcomes." (PMID 38973477, 2024). "The experimental results of PCR showed that compared to normal samples, PRKG1‐AS1 and SH3BP5‐AS1 were significantly upregulated while LINC00567, LINC00996, MTOR‐AS1, RAB11B‐AS1, RPS6KA2‐AS1, and ZNF451‐AS1 were significantly downregulated in tumor tissues." (PMID 33660438, 2021). "In addition, LINC00567, LINC00996, MTOR‐AS1, RAB11B‐AS1, RPS6KA2‐AS1, and ZNF451‐AS1 were significantly downregulated in tumor samples compared with normal samples." (PMID 33660438, 2021). "In addition, Linc00996 may repress the tumorigenesis and metastasis of LUAD via some tumor-related signaling pathways, such as antigen processing and presentation, JAK-STAT3, and cell adhesion." (PMID 36118847, 2022). "On the basis of the principle of ceRNA hypothesis, C22orf34, RFPL1S, and LINC00996 shared same expression patterns as CXCL10, CXCL9, CCL5, FCGR3A, and CCR2, all which were upregulated in tumor tissues of PTC with HT compared with those without HT." (PMID 36266640, 2022).
cancer (7 papers, 2021 to 2024). A tumor composed of atypical neoplastic, often pleomorphic cells that invade other tissues. "By mining TCGA and other databases, as well as our own experimental validation, we confirmed that Linc00996 is downregulated in cancer tissues and is a favorable prognostic factor in LUAD." (PMID 36118847, 2022). "Initially, LINC00996 expression was examined in the Cancer Cell Line Encyclopedia (CCLE)." (PMID 39220187, 2024). "Thus, LINC00996 should be further studied in the context of cancer." (PMID 35610596, 2022). "Despite several kinds of research that have illuminated the role of LINC00892 and LINC00996 in multiple cancers, their function in NSCLC has not been studied and deserves further investigation considering its significant prognostic value in NSCLC." (PMID 34861872, 2021). "In this study, several ARlncRNAs included in the modeling process have been already reported in various malignant tumors, such as CARD8-AS1, AC060780.1, AC123595.1, UGDH-AS1, LINC00996, LINC00861, AL606489.1, HLA-DQB1-AS1, LINC00654, and LINC00847." (PMID 34956321, 2021). "However, research on AC005838.2, AC027020.2, and LINC00996 regarding their prognostic value in cancer and contributions to senescence is lacking." (PMID 36406130, 2022).
LINC00996 also shares sentences with these, for which no sentence is quoted: ovarian carcinoma (2 papers); autoimmune thyroid disease (1); bladder cancer (1); head and neck cancer (1); multiple myeloma (1).